BRAF (B-Raf proto-oncogene, serine/threonine kinase)
Diseases named in the same sentence as BRAF in open-access papers (continued):
Sharing a sentence is not in itself a finding about the gene and the disease.
metastatic melanoma (continued). "Expectedly, BRAF and MEK inhibitors (or their combination) have been poorly explored as potential therapeutic strategies in metastatic melanomas harboring this rare mutation." (PMID 32754440, 2020). "In fact, for all the samples, gDNA obtained from routine molecular testing of BRAF in metastatic melanoma and extracted with different methods in the two laboratories proved to be good reference material for the evaluation of this panel." (PMID 33317587, 2020). "For example, NCT01400451 is investigating the efficacy and safety of vemurafenib (BRAF inhibitor) in combination with ipilimumab (CTLA-4-Ab) for the treatment of patients with metastatic melanoma expressing an activated mutant form of BRAF V600E." (PMID 32260561, 2020). "On 1 October 2015, ipilimumab in combination with nivolumab received FDA approval for BRAF V600 wild-type unresectable or metastatic melanoma based on CheckMate-069, a randomized, phase 2 study (Category 1)." (PMID 32245016, 2020). "We developed a PDX library of BRAF-mutant metastatic melanoma, and a high-throughput drug-screening (HTDS) platform utilising clinically relevant drug exposures." (PMID 31857724, 2020). "In clinical practice, BRAF inhibitors, including trametinib and dabrafenib, are widely used to treat and prevent metastatic melanoma." (PMID 32352219, 2020). "At this moment, these molecules are investigated in several clinical trials for patients with metastatic melanoma alone or in combination with BRAF and/or MEK inhibitors (NCT02065063, NCT01781572)." (PMID 32575838, 2020). "NCT02902042 is a phase I/II study investigating the efficacy and safety of encorafenib (BRAF inhibitor) combined with binimetinib (MEK inhibitor) and pembrolizumab (anti-PD-1 antibody) in patients with BRAF V600-mutated unresectable or metastatic melanoma." (PMID 32260561, 2020). "A phase III study (NCT02967692) is investigating the safety and efficacy of the anti-PD-1 antibody spartalizumab in combination with the BRAF inhibitor dabrafenib and the MEK inhibitor trametinib in untreated patients with BRAF V600-mutant metastatic melanoma." (PMID 31947592, 2020). "BRAF inhibitors (BRAFi) have been approved for the clinical treatment of BRAF-mutant metastatic melanoma." (PMID 32371878, 2020). "Combination therapy using BRAF and MEK inhibitors such as cobimetinib is nowadays one of the first line treatment for patients with BRAF V600E metastatic melanoma." (PMID 32858889, 2020). "In metastatic melanoma the combination treatment of BRAF inhibitor dabrafenib and MEK inhibitor trametinib is used to treat patients with BRAF(V600E) mutant tumors successfully for many years." (PMID 32591993, 2020). "We analysed 142 plasma samples from metastatic melanoma patients prior to commencement of systemic therapy: 70 were treated with BRAF/MEK inhibitors and 72 with immunotherapies." (PMID 33339135, 2020). "Nevertheless, a significant number of patients with BRAF V600 metastatic melanoma experience relapse within a few months after treatment with the combination of BRAF and MEK inhibitors." (PMID 31599373, 2020). "Vemurafenib and Dabrafenib are selective oral BRAF inhibitors (BRAFi) that have been licensed by the Food and Drug Administration (FDA, Hampton, VA, USA) for the treatment of unresectable or metastatic melanomas harboring activating BRAFV600 mutations." (PMID 32054078, 2020). "Nearly half of patients with metastatic melanomas harbor a valine–glutamine substitution in codon 600 of the serine/threonine kinase BRAF." (PMID 32526884, 2020). "BRAF and MEK inhibitors in combination with PD-1 blockade therapy showed a 73% overall response rate (ORR) and 93% stable disease in BRAF V600-mutated metastatic melanoma." (PMID 33194652, 2020). "Targeted therapy with BRAF and MEK inhibitors has improved the survival of patients with BRAF-mutated metastatic melanoma, but most patients relapse upon the onset of drug resistance induced by mechanisms including genetic and epigenetic events." (PMID 32967672, 2020).
metastatic melanoma (continued). "Vemurafenib and dabrafenib BRAF inhibitors (BRAFi) have improved the outcomes of patients with BRAF-mutant metastatic melanoma." (PMID 32604720, 2020). "These cells lines were established from metastatic melanoma patient-derived tumor samples, including BRAF-inhibitor-resistant tumors, to represent the clinical heterogeneity of unresectable metastatic cutaneous melanoma both before and during treatment." (PMID 33105692, 2020). "Other studies in patients with metastatic melanoma treated with BRAF-i alone or in combination with MEK-i described similar observations." (PMID 32367253, 2020). "While the introduction of BRAF inhibitors such as Vemurafenib, Dabrafenib and Encorafenib has recently revolutionized the treatment landscape of metastatic melanoma, the results in the treatment of CRC were largely unsatisfactory." (PMID 32326305, 2020). "Altogether, TT with BRAF inhibitors and MEK inhibitors provides rapid disease control with high response rates in patients with BRAFV600E-mutated metastatic melanoma." (PMID 32825357, 2020). "Vemurafenib, dabrafenib, and encorafenib are BRAF inhibitors (BRAFi) approved by the US Food and Drug Administration (FDA) to treat patients with BRAFV600E mutated metastatic melanomas." (PMID 32526884, 2020). "BRAFi, either alone or in combination with MEKi, represents therapeutic options for the treatment of BRAF-mutant metastatic melanomas." (PMID 32371878, 2020). "To do so, we identified a clinical practice-compatible protocol for the isolation of EV-DNA and assessed BRAF gene status on plasma samples from metastatic melanoma patients at the beginning and during BRAFi therapy." (PMID 32978468, 2020). "Here we present a case series of metastatic melanoma patients who stopped BRAF targeted therapy after obtaining CR." (PMID 33139839, 2020). "This study demonstrates the potential of digital pathomics to incorporate immune cell spatial distribution within metastases and RNAseq analysis to predict clinical response to BRAF inhibition in metastatic melanoma." (PMID 32528881, 2020). "In a phase 3 study, 418 previously untreated patients with metastatic melanoma and wild-type BRAF received either nivolumab or dacarbazine." (PMID 32825357, 2020). "PDXCs and corresponding PDXs from metastatic melanoma patients that progressed on standard-of-care therapy demonstrated similar resistance patterns to BRAF and MEK inhibitor therapy." (PMID 31857724, 2020). "Targeted therapy, i.e., BRAF inhibitors combined with MEK inhibitors, induce rapid responses and high response rates in patients with metastatic melanoma in the presence of a BRAF-V600 mutation." (PMID 31947592, 2020). "In 2018, the FDA approved the BRAF/MEK combination encorafenib plus binimetinib for BRAFV600E- and BRAFV600K-mutated metastatic melanoma based on more durable results from a Phase 3 clinical trial." (PMID 32411231, 2020). "These eight BRAF-mutant metastatic melanoma models were chosen for the remainder of the study, because they produced the most consistent tumour growth in mice and PDXC yield amendable to HTDS." (PMID 31857724, 2020). "A combination of BRAF and MEK inhibitors has been employed for the treatment of metastatic melanomas harboring the BRAFV600E mutation." (PMID 32626712, 2020). "In total, 418 previously untreated patients with metastatic melanoma and wild-type BRAF received either nivolumab or dacarbazine." (PMID 31947592, 2020). "In a clinical study, the confirmed objective response rate of BRAF V600 wild-type metastatic melanoma patients, who received the combination therapy of nivolumab and ipilimumab, was 61.1% (44/72) compared with 10.8% (4/37) in the ipilimumab monotherapy group." (PMID 31297335, 2019). "One example is Vemurafenib, a BRAF kinase inhibitor, FDA approved when combined with the MEK inhibitor Cobimetinib for treatment of metastatic melanoma harboring BRAF V600 mutation, also blocks the recruitment of MDSCs." (PMID 30781344, 2019).
metastatic melanoma (continued). "In June 2018, the FDA approved the combination of BRAF inhibitor encorafenib and the MEK inhibitor binimetinib for treatment of patients with unresectable or metastatic melanoma with a BRAF-V600E or -V600K mutation." (PMID 31058077, 2019). "Despite advances with BRAF inhibitors and immunotherapy, many patients still succumb to metastatic melanoma." (PMID 31019203, 2019). "The higher expression of DNMT1 and EZH2 is concordant with previous observations in BRAF-mutated cells, such as it is the case for WM266-4, described to participate in the hypermethylated phenotype of metastatic melanoma cells (and personal observations)." (PMID 30651148, 2019). "In 2013, success of the Phase III clinical trial ‘BREAK-3’ led to the FDA approval of dabrafenib for the treatment of patients with mutant V600 BRAF metastatic melanomas." (PMID 30975211, 2019). "The majority of studies have been applied to patients treated with BRAF inhibitors, via monitoring of the singular BRAFV600 mutation, predicting response to therapy and prognosis in metastatic melanoma." (PMID 31330795, 2019). "For example, BRAF inhibitor, vemurafenib, used for treating metastatic melanoma with overall good clinical outcome, was manifested to induce unusual photosensitivity in patients." (PMID 30820346, 2019). "Recently, BRAF inhibitors (iBRAF), such as vemurafenib, dabrafenib and encorafenib, have revolutionized the treatment of BRAF V600E metastatic melanoma in monotherapy or in combination with other drugs." (PMID 31661924, 2019). "The biological rationale of combining or sequencing ICB with TT in metastatic melanoma stems from a growing body of evidence supporting the favorable immune effects created by the oncogene-targeted therapies directed at the BRAF/MAPK pathway." (PMID 30621779, 2019). "Surprisingly, two patients with stage IIIB/C metastatic melanoma benefited from T-VEC after disease progression with multiple therapies including BRAF/+MEK inhibition, immune checkpoint blockade, and GM-CSF." (PMID 31134073, 2019). "Approximately 65% of patients with metastatic melanoma have RAS–RAF–MEK–ERK pathway mutations, and 40% have BRAF V600 activating mutations." (PMID 31817473, 2019). "The MEK inhibitors cobimetinib and trametinib are used in combination with BRAF inhibitors to treat metastatic melanoma but increase rates of hemorrhage relative to BRAF inhibitors alone." (PMID 30252580, 2019). "Tumor-associated B-cells have been identified in both primary and metastatic melanoma lesions and the release of insulin-like growth factor by TABs leads to resistance to BRAF or MEK inhibitors." (PMID 31554169, 2019). "The development of BRAF and MEK inhibitors as treatment options for patients with BRAF-mutant tumors has contributed to improve the median overall survival of patients with metastatic melanoma." (PMID 31635389, 2019). "This prospective population-based study focuses on the clinical outcomes of BRAF-mutant metastatic melanoma patients with baseline serum LDH of ≥2× ULN treated with first-line targeted therapy." (PMID 31817189, 2019). "In BRAFV600mut metastatic melanoma, the combination of BRAF and MEK inhibitors (BRAFi, MEKi) has undergone multiple resistance mechanisms, limiting its clinical benefit and resulting in the need for response predicting biomarkers." (PMID 31426590, 2019). "Two therapeutic agents for targeting BRAF in metastatic melanoma have been approved by the FDA; but a majority of patients are likely to develop drug resistance." (PMID 31671773, 2019). "On the other hand, with advances in the genotype-directed treatment, specific and highly effective small-molecule inhibitors targeting BRAF and MEK mutants have been developed and used in the treatment of BRAF-mutant metastatic melanoma patients." (PMID 31138783, 2019). "In the past decade, treatment options for metastatic melanoma have significantly increased with the arrival of BRAF inhibitors and BRAF/MEK combination therapy." (PMID 31780644, 2019).
metastatic melanoma (continued). "In the last few years, therapies targeting this pathway, such as those involving a BRAF inhibitor (BRAFi), have greatly improved the clinical outcome of BRAFV600mut metastatic melanoma." (PMID 31426590, 2019). "Combined therapy with BRAF and MEK inhibitors is approved for BRAF mutant cutaneous metastatic melanomas." (PMID 31024839, 2019). "These accumulative findings suggest that magnolol is a potential therapeutic option for treating BRAF‐mutant metastatic melanoma in combination with current targeted therapies." (PMID 30793515, 2019). "Through preclinical study, dabrafenib plus trametinib had shown high antitumor activity in BRAF V600E mutation cell lines, and clinically, BRAF plus MEK inhibitors revealed improved clinical outcome in patients with BRAF V600E mutant metastatic melanoma." (PMID 31023335, 2019). "Data from all patients with BRAF-mutant metastatic melanoma with a highly elevated serum LDH at baseline (≥2× upper limit of normal) receiving first-line targeted therapy between 2012 and 2019 in the Netherlands were collected." (PMID 31817189, 2019). "We then investigated the effects of PXR activation on the pharmacokinetics of the anticancer drug dabrafenib, used as the standard of care in the UK for the treatment of BRAF mutant metastatic melanoma." (PMID 30910785, 2019). "Vemurafenib induces significant clinical responses in more than half of patients with previously treated BRAF V600-mutant metastatic melanoma, where the median overall survival was approximately 16 months." (PMID 31652660, 2019). "Despite the efficacy of BRAF-targeted and PD-1-related immune therapies in treating metastatic melanoma, a significant number of patients exhibit resistance." (PMID 31354491, 2019). "When performing class comparison between BRAF mutant and wild-type metastatic melanoma samples, metastases showing a Th17 phenotype were preferentially BRAF mutated." (PMID 30800130, 2019). "Conservative estimates suggest that about 20% of BRAF mutant metastatic melanoma patients develop brain metastases." (PMID 30886831, 2019). "FDA approved BRAF inhibitors for metastatic melanoma include Vermurafenib, Dabrafenib, Trametinib, which target BRAF V600E or V600K, while Cobimetinib specifically inhibits MEK." (PMID 31890286, 2019). "Despite markedly improved treatment options for metastatic melanoma, resistance to targeted therapies such as BRAF inhibitors (BRAFi) or BRAFi plus MEK inhibitors (MEKi) remains a major problem." (PMID 29266761, 2018). "For example, amplification of BRAF via copy number gains was found in 8% of the tumor samples from metastatic melanoma treated with BRAF inhibitors." (PMID 31093356, 2018). "Our results validate findings similar to human metastatic melanoma patient samples that developed acquired resistance to BRAF inhibition." (PMID 29541385, 2018). "Acquired resistance of metastatic melanoma (MM) tumors to BRAF V600E inhibitors (BRAFi’s) is commonplace in the clinic." (PMID 29568360, 2018). "The mutated BRAF oncogene represents a therapeutic target in metastatic melanoma, where a mutated NRAS oncogene is a biomarker of poor outcome and resistance to treatment with BRAF inhibitors." (PMID 30546839, 2018). "In this study, we evaluated the fully automated ready-to-use IdyllaTM PCR-based system for identification of BRAF V600 and NRAS mutations in plasma samples from patients with metastatic melanoma at baseline and during the course of treatment." (PMID 30546839, 2018). "Depending on the mutational status, BRAF and MEK inhibitor combinations or immune checkpoint inhibitors are current first-line treatments for metastatic melanoma." (PMID 29794999, 2018). "A left axillary lymph node dissection was performed and revealed 2 of 19 lymph nodes involved with metastatic melanoma, BRAF wild type, the largest of which measured 10.1 cm." (PMID 29898784, 2018).